IL6 (interleukin 6)
Diseases named in the same sentence as IL6 in open-access papers (continued):
Sharing a sentence is not in itself a finding about the gene and the disease.
pneumonia (continued). "Based on these findings, the potential benefits of IL-6- and G-CSF-targeted therapy in the treatment of influenza-associated pneumonia must be explored in the future." (PMID 35382755, 2022). "In the future, the use of IL-6R and G-CSFR antagonists in the treatment of influenza-associated pneumonia patients with high levels of IL-6 and G-CSF needs to be explored." (PMID 35382755, 2022). "These cytokines will cause the immune system to produce an excessive attack on the human body and cause severe pneumonia, which mainly include interleukin-6 (IL-6), interleukin-1 (IL-1), tumor necrosis factor-α (TNF-α), and so on." (PMID 36146616, 2022). "AC larval migration caused fatal lung injury (pneumonia) during acute and early infection phases, along with significant activation of Stat3/IL-6 signaling." (PMID 35617354, 2022). "IL-6 and G-CSF showed a strong and positive correlation with poor prognosis in influenza-associated pneumonia patients." (PMID 35382755, 2022). "It is known that overproduction of IL-6 promoted pulmonary fibrosis and respiratory and multi-organ failure and has also been linked with pneumonia." (PMID 36012146, 2022). "This study was designed to access the diagnostic value of interleukin-6 (IL-6) for pneumonia within the first 5 days after cardiac surgery in adults." (PMID 35794529, 2022). "For example, MR drug safety studies have in the past substantiated the causal relationship between inhibition of IL‐6 signalling and increased risk of pneumonia." (PMID 33393675, 2021). "IL-6 is considered as a biomarker associated with pneumonia diagnosis and with bacterial infection and outcome in adult and pediatric CAP patients." (PMID 34602860, 2021). "This is confirmed in recent studies revealing lower IL-6 levels in atypical pathogen pneumonia than in pneumonia caused by typical bacterial infections, such as Streptococcus pneumonia." (PMID 33673270, 2021). "High serum IL-6 levels are associated with the presence of pneumonia, disease severity, and poor prognosis." (PMID 34109187, 2021). "One prospective cohort study has shown that patients with pneumonia who left the hospital with higher interleukin-6 levels at discharge were associated with increased subsequent mortality despite clinical recovery." (PMID 32668753, 2020). "These patients also manifest a hyper-inflammatory state or “cytokine storm” characterized by elevated levels of inflammatory markers such as the C-reactive protein (CRP) and interleukin-6 which have been linked to the severity of pneumonia and mortality." (PMID 33312811, 2020). "In our study, we found S. aureus infection triggered severe pneumonia, which caused a great rise in pro-inflammatory factors, such as IL-1β, IL-6, TGF-β, MIP-2, MCP-1 and TNF-α in bronchoalveolar lavage fluid." (PMID 33255656, 2020). "We postulate that her siltuximab therapy blocked the IL-6-associated fever and constitutional symptoms that normally are a hallmark of pneumonia." (PMID 32766009, 2020). "This study is aimed at assessing the diagnostic value of hs-CRP, PCT, and IL-6 in differentiating severe pneumonia caused by RSV alone and RSV with bacterial coinfections among Vietnamese children under 5 years old." (PMID 32462018, 2020). "Higher proportion of neutrophil, lower proportion of lymphocytes, lower T cell count, and higher serum level of IL-6 were significantly associated with the risk of developing pneumonia." (PMID 33239109, 2020). "In patients with severe pneumonia, apolipoprotein-A1 decrease was associated with acute inflammation and the “cytokine storm” with an increase in IL6 and acute phase proteins such as CRP and haptoglobin." (PMID 33216772, 2020). "Lymphopenia, elevated serum markers (C-reactive protein, procalcitonin, IL-6, D-dimer), and chest-X-ray findings consistent with pneumonia are linked to worse prognosis." (PMID 32550702, 2020). "The IL-6-572 polymorphism was detected, and the impacts of gene polymorphism difference on pediatric pneumonia were observed." (PMID 31970102, 2019).
pneumonia (continued). "In contrast to homeostatic conditions, we report an increase in cytokine expression during pneumonia in the Zcchc6-deficient mice compared to wildtype controls, particularly IL-6 and CXCL1." (PMID 28665939, 2017). "Lung neutrophils from mice with pneumonia showed increased expression of genes that encode a number of mediators, including the important pro-inflammatory cytokines IL-1α, IL-6, TNF and CXCL1 (KC)." (PMID 28900269, 2017). "In support of the role of inflammation, levels of interleukin 6 measured at the time of hospital discharge in patients with pneumonia identify patients at greater risk of cardiovascular related mortality within a one year follow-up." (PMID 29028810, 2017). "In particular, high levels of interleukin (IL)-6, IL-8, and IL-10 have been detected in patients with severe pneumonia and excess IL-6 and IL-10 was associated with increased mortality (from 4.8 to 11.4 %)." (PMID 27716262, 2016). "In patients with severe pneumonia and pneumonia, IL-6 levels were associated with vomiting; however, in the severe pneumonia group, IL-6 levels were also associated to dyspnea, suggesting that this cytokine plays a role in pneumonia severity." (PMID 27905908, 2016). "At admission, IL-6 serum levels were high in mild or severe pneumonia, and was associated to vomiting (P = 0.019) in both groups; and also to dyspnea (P = 0.012) and white blood cell count (P = 0.045) in patients with severe pneumonia." (PMID 27905908, 2016). "Older adults who have higher than age-average levels of the cytokines TNF and IL6 in their circulation have a much higher risk of acquiring pneumonia than their peers who have lower than age-average levels." (PMID 26766566, 2016). "Published data on the associations between three well-characterized polymorphisms in the interleukin 6 and 10 (IL-6 and IL-10) genes and the risk of pneumonia are inconclusive." (PMID 25708204, 2015). "In view of the number of included articles, subgroup analyses were undertaken only for the IL-6 gene -174 C/G polymorphism, with regard to age, pneumonia type, ethnicity, sample size and quality score." (PMID 25708204, 2015). "To generate more information, we carried out a meta-analysis of all of the available case-control studies to investigate the association of genetic polymorphisms of IL-6 and IL-10 with the risk of pneumonia." (PMID 25708204, 2015). "In the analysis of the IL-6 gene -174 C/G polymorphism and pneumonia risk, the resultant symmetrical funnel shape was consistent with the absence of publication bias in the funnel plot for contrasts of C versus G (P-Egger test = 0.475)." (PMID 25708204, 2015). "In AEP−/− mice, significant inhibition of cytokine and chemokine secretion associated with influenza virus-induced pneumonia, including keratinocyte chemo-attractant (KC), interleukin 6 (IL-6), and interleukin 12 (IL-12), was detected compared to wt mice." (PMID 22916010, 2012). "This PCT-threshold was more sensitive and specific than CRP, IL-6, or white blood cell count for differentiating bacterial and viral causes of pneumonia." (PMID 21385367, 2011). "The pronounced IL-6 upregulation in canine endothelial cells could indicate greater susceptibility to pneumonia and potentially chronic changes such as fibrosis, whereas the moderate response in fox endothelial cells suggests a lower risk of such damage." (PMID 40529303, 2025). "Interestingly however, IL6-mediated genetic downregulation of IL-6 signaling was associated with lower risk of hospital admission due to pneumonia, in contrast to a higher risk linked to IL6R perturbation." (PMID 40858837, 2025). "Serum PCT >86.66 pg/ml and serum IL-6 > 18.06 ng/L also showed excellent diagnostic power, with 96.0% sensitivity and 100.0% specificity for each, further supporting their clinical relevance in detecting pneumonia." (PMID 41018059, 2025).
pneumonia (continued). "Similarly, IL-6 emerged as a strong predictor, with a hazard ratio of 4.25 (CI: 2.07–9.53) and a p-value of less than 0.001, suggesting a fourfold increase in pneumonia risk." (PMID 39202577, 2024). "Furthermore, our result agrees with Ulhaq ZS and Soraya GV, 2020 who found that individuals who are carrier for C allele of the − 174G / C (rs1800795) polymorphism associated with high IL6 production and severe pneumonia." (PMID 39354444, 2024). "In pneumonia, IL-6 was shown to be associated with mortality and disease severity." (PMID 37733154, 2023). "Serum IL-6 and IL-10 have been suggested to be directly associated with the development of pneumonia symptoms, and their expression levels in the serum can indirectly reflect the development of pneumonia in vivo." (PMID 37764047, 2023). "Additionally, the same correlation was demonstrated between the LUSS and IL-6 levels, a fact already proved in the study based on newborns with COVID-19-associated pneumonia." (PMID 37892994, 2023). "In a prospective, population-based cohort of American elderly, higher baseline levels of tumor necrosis factor alpha (TNF-α) and interleukin 6 (IL-6) were associated with an increased pneumonia risk during follow-up, even after adjustment for traditional risk factors and comorbidities." (PMID 35757724, 2022). "Importantly, IL-6 and G-CSF were identified as significant predictors of the severity of influenza-associated pneumonia." (PMID 35382755, 2022). "In terms of cytokines, the literature indicates that serum IL-6 levels may be associated with infection - pneumonia, bacterial peritonitis, and urinary tract infection (UTI) - and death and AKI in patients with liver cirrhosis." (PMID 34846061, 2022). "IL-6 may help clinicians determine a patient's risk of developing pneumonia early and these patients can be more targeted for further monitoring and treatment with antibiotics." (PMID 35794529, 2022). "There is evidence that vitamin D reduces the synthesis of pro-inflammatory cytokines interferon (IFN) and interleukin-6 (IL-6) with concomitant reduction in inflammation and the risk of lung lesions due to pneumonia, and increases the synthesis of anti-inflammatory cytokines." (PMID 35631138, 2022). "Furthermore, SIRS and IL-6 levels were found to be associated with an increased risk of pneumonia, multiple organ failure, and mortality." (PMID 35574553, 2022). "Importantly, our findings showed a significant increase in IL-6 and G-CSF levels in influenza-associated pneumonia patients with a poor prognosis." (PMID 35382755, 2022). "In addition, polymorphism in IL-6 -174G/C was associated with higher IL-6 production and severe pneumonia." (PMID 34649460, 2021). "In addition, high IL-6 blood level is associated with increased mortality in less than 5-year-old patients with pneumonia requiring mechanical ventilation." (PMID 34708133, 2021). "The laboratory abnormalities including lymphopenia; elevated acute biochemical markers, that is, C-reactive protein; procalcitonin; interleukin-6; D dimer; and radiological findings of ground glassing; pneumonia; and fibrosis are associated with poor prognosis." (PMID 34616572, 2021). "IL-6-174C, higher IL-6 level, pneumonia severity (C allele vs. G allele)." (PMID 33158051, 2020). "Due to the lack of data in up to half of our patients, we were unable to analyze the impact of other inflammatory/procoagulant biomarkers, such as ferritin, IL-6 and D-dimer on the risk of developing severe pneumonia and death, although they did show a clear trend in univariate analysis." (PMID 32864192, 2020). "IL-6 gene polymorphism might be related to the pediatric pneumonia and the population with G allele at this locus may be more prone to pediatric pneumonia." (PMID 31970102, 2019).
pneumonia (continued). "Therefore, in this study, the impact of IL-6 gene polymorphism on pediatric pneumonia was examined, hoping to find pediatric pneumonia screening indicators and to conduct better prevention and treatment of pediatric pneumonia." (PMID 31970102, 2019). "To summarize, loss of IL-6 increased the susceptibility of bacterial superinfection after flu and weaken pathogen clearance, both which result in the early dissemination of bacteria in animals with co-infected pneumonia." (PMID 32038632, 2019). "IL-6 is a critical inflammatory cytokine that is closely linked with the occurrence and development of infection; its protein levels are related to the severity of pneumonia and patient prognosis." (PMID 30761162, 2018). "In addition to promoting inflammation, lung damage and edema, IL-6 deficiency alters bacterial clearance in experimental pneumonia and is associated with increased mortality following LPS aspiration." (PMID 28424078, 2017). "In the present study, the cytokines, TNF, IL-1β, IL-6, IL-8, IL-12p70, IFN-γ, IL-17A, IL-10 and IL-5, were detected in the serum of children with pneumonia and severe pneumonia at hospital admission, and IL-6 was the only cytokine associated with disease severity." (PMID 27905908, 2016). "In patients with severe pneumonia, the IL-6 levels were positively associated with high levels of leukocytes while the levels of TNF and IL-1β were associated with monocytes, possibly related to the recruitment and differentiation of macrophages at the site of inflammation." (PMID 27905908, 2016). "Susceptibility to pneumonia correlates with increased levels of IL6 and TNF before an infection." (PMID 26766566, 2016). "In addition, systemic increase in IL-6 and IL-10 in pneumonia is associated with the worse prognosis." (PMID 24696530, 2014). "This survival advantage is associated with decreased pneumonia-induced intestinal atrophy and epithelial apoptosis, preservation of the intestinal proliferative response, and a reduction in circulating levels of the proinflammatory cytokines IL-6 and G-CSF." (PMID 23145105, 2012). "Indeed, elevated IL-6 levels were reported to be associated with systemic inflammation, pneumonia, hypoxemia, and poor prognosis, which agrees with our present findings that the levels of IL-6 were significantly higher in vaccinated or unvaccinated patients with pneumonia than in those without." (PMID 38694512, 2024). "Furthermore, we demonstrate that the patients with the larger scores in CURB-65 are the ones with the highest SARS-CoV-2 plasma viral load and that this pneumonia severity scale is significantly associated with inflammation, specifically with the cytokine IL-6." (PMID 36769445, 2023). "However, the efficacy of rapid serum IL-6 measurements and early identification of elderly patients with pneumonia at-risk of respiratory failure remains unknown." (PMID 37214473, 2023). "Accordingly, anti-IL6 therapies including sarilumab, tocilizumab and clazakizumab, as well as biologics targeting terminal components of the complement cascade, such as eculizumab and ravulizumab, are in various clinical trial phases for treating COVID-19-associated pneumonia." (PMID 33782412, 2021). "Various inflammatory states such as pneumonia, encephalitis, malaria, and adult respiratory distress syndrome are associated with the development of inflammatory cytokines such as interleukin 1 (IL-1) and interleukin 6 (IL-6) which have been shown to be associated with the release of AVP." (PMID 25853137, 2015). "Thus, SIRS associated with RSV infection may be characterized by progression of severe pneumonia caused by hematogenous actions of elevated IL-6 on the lung and encephalopathy of the cytokine storm type resulting from similar actions of IL-6 on the brain." (PMID 23354937, 2013). "The pro-inflammatory cytokine IL-6 has predictive potential of severity in a variety of diseases, e.g. heart disease, pneumonia." (PMID 40114261, 2025).
pneumonia (continued). "Salivary and serum IL-6, IL-10, and PCT show promising diagnostic potential for pediatric pneumonia when compared to healthy controls." (PMID 41018059, 2025). "This vaccine led to a 60% survival rate and reduced bacterial colonization in the spleen and lungs, and it lowered the pro-inflammatory cytokines (TNF-α, IL-6, IL-12) in a pneumonia model." (PMID 40076637, 2025). "In contrast, the low heterogeneity (I2 < 30%) across studies examining IL-6 and S100B levels in patients with pneumonia indicates more uniform findings." (PMID 41585373, 2025). "Serum inflammatory cytokine assays indicated significantly elevated levels of TNF-α, IL-1β, and IL-6 in the pneumonia group compared to the control group (p < 0.001), suggesting that pathogen infection triggered a systemic inflammatory response." (PMID 41300746, 2025). "It has also shown efficacy in preventing severe pneumonia, potentially by acting on the IL-6 trans signal and HM-GB1 system." (PMID 40918117, 2025). "Numerous studies have shown that levels of TNF‐α, IL‐1β, and IL‐6 are significantly elevated in the serum or bronchoalveolar lavage fluid of patients with acute pneumonia or in LPS‐induced animal models." (PMID 40144560, 2025). "None of the patients with Chlamydia pneumoniae, Moraxella catarrhalis, or Haemophilus influenzae-related pneumonia had serum IL-6 levels greater than 500 pg/mL." (PMID 40136649, 2025). "To obtain an initial understanding of how SRT1720 affects the inflammatory response in the airways during Klebsiella-induced pneumonia, we measured cytokines (IL-6, TNF-α) and chemokines (CXCL1 and CXCL2) in BALF obtained 24 or 42 h after infection." (PMID 41096578, 2025). "Among them, IL-6 contributes to both pneumonia pathogenesis and iron restriction during infection by increasing hepcidin that causes iron restriction in blood and traps the iron intracellularly." (PMID 40236451, 2025). "Research demonstrates that this medication reduces viral load, lung index, and serum IL-6 levels in mice with influenza-induced pneumonia, and effectively ameliorates the pathological damage to lung tissues caused by the virus." (PMID 40474974, 2025). "Animal studies have shown that pneumonia increases hepcidin expression, dependent on IL-6 signaling." (PMID 40615660, 2025). "Within Firmicutes we recorded a selective loss of unclassified_Lachnospiraceae and Blautia, two clades whose abundance inversely correlates with IL-6/IL-1β concentration in murine pneumonia models." (PMID 41311834, 2025). "Among these factors, the most critical is the activation of the interleukin-6 (IL-6)–hepcidin axis during the acute phase of pneumonia, which profoundly disrupts iron metabolism and impairs heme synthesis." (PMID 40615660, 2025). "In sepsis and pneumonia models, prophylactic vaccination produced significant reductions in lung bacterial colonization and the levels of pro-inflammatory cytokines (IL-6, TNF-α and IL-1β), resulting in 100% survival over 14 days." (PMID 40076637, 2025). "As a pro-inflammatory cytokine, IL-6 is often elevated in severe pneumonia, reflecting exacerbated airway inflammation, increased mucus production, and impaired ciliary function, all of which significantly raise the incidence of ACD." (PMID 41234411, 2025). "Elevated IL-6 in children with pneumonia reinforce its value as a sensitive biomarker of systemic inflammation and highlight its pathophysiological relevance in pneumonia." (PMID 41018059, 2025). "Pro-inflammatory cytokines, such as IL-6 and IL-10, increase in patients with pneumonia according to disease severity." (PMID 40807081, 2025). "PCT and IL-6 were inferior at predicting poor outcome in infants compared to older children with pneumonia in Bhutan35." (PMID 40715696, 2025). "Elevated levels of IL-10, IL-8, and IL-6 cytokines emerged as robust predictors of mortality in young adults with severe pneumonia due to SARS-CoV-2 infected." (PMID 38268832, 2024).